CFTR (CF transmembrane conductance regulator)
Diseases named in the same sentence as CFTR in open-access papers (continued):
Sharing a sentence is not in itself a finding about the gene and the disease.
bronchiectasis (continued). "CONCLUSIONS: A CFTR activity of the nasal surface epithelium in the lower quartile is typical for people with idiopathic bronchiectasis, but further CFTR-independent inherited susceptibilities and external insults are necessary to materialize the emergence of bronchiectasis." (PMID 41776502, 2026). "Several studies have shown that heterozygous carriers of CFTR mutations have an increased risk of pancreatitis, male infertility, and the development of respiratory infections such as chronic bronchitis, sinusitis, bronchiectasis, and lung cancer." (PMID 40724872, 2025). "Besides, several studies have also reported 6 genetic risk factors associated with the development of bronchiectasis, and these studies have focused on CFTR and HLA variants." (PMID 38966529, 2024). "Heterozygous carriers of a CFTR variant may be at raised risk of developing bronchiectasis, asthma, allergic bronchopulmonary aspergillosis, and chronic rhinosinusitis." (PMID 38339178, 2024). "The positive changes in MRI-derived mucus plugging and wall thickening/bronchiectasis score have been shown to be associated with the improvement of CFTR function, which might reflect the resolution of inflammation in CF patients." (PMID 37548691, 2024). "As such, in a disease state—with structural damage as demonstrated by the presence of bronchiectasis—the opportunity for FEV1 improvement may be limited despite correction of the underlying CFTR defect." (PMID 37325471, 2023). "Reversal of bronchiectasis, even in the context of continued airway infection, suggests a more dynamic relationship between the instigating factor(s) causing bronchiectasis (e.g., CFTR dysfunction, as in these cases) and the ongoing airway changes as measured on HRCT." (PMID 37323158, 2023). "The question remains whether increasing CFTR function will also improve bronchiectasis of other causes." (PMID 37323158, 2023). "Possibly, a single mutation in CFTR combined with other genetic and environmental factors might be involved in the pathogenesis of bronchiectasis." (PMID 30151190, 2018). "CFTR mutations have been reported with higher frequency in bronchiectasis population." (PMID 30151190, 2018). "Our results suggest that several variants in ENaCβ and γ genes might be deleterious for ENaC function and lead to bronchiectasis, especially in patients who are trans-heterozygotes for ENaCβ/CFTR mutations or variants." (PMID 18507830, 2008). "However, research indicates that only 15.4% of patients diagnosed with both bronchiectasis and rheumatoid arthritis display mutations in the CFTR gene, suggesting that these mutations may have a minimal impact." (PMID 38783321, 2024). "We wanted to resolve the role of CFTR dysfunction in people with idiopathic bronchiectasis by nasal potential difference (NPD) measurements." (PMID 41776502, 2026). "Most people with CRMS/CFSPID remain healthy, however, a minority will convert to a CF diagnosis or develop CFTR‐related disorders (CFTR‐RD) later in life (e.g. bronchiectasis)." (PMID 40844078, 2025). "In some individuals with a single CFTR pathogenic variant, CFTR-related disorders (CFTR-RDs) happen, which include CBAVD, idiopathic chronic pancreatitis, bronchiectasis, and susceptibility to certain infections." (PMID 41431510, 2025). "Another Italian study reported a patient with CFTR-RD who harboured the c.489+3A>G/p.Phe508del in trans, exhibited a sweat chloride level of 40 mmol/L, and presented with isolated bronchiectasis." (PMID 40301948, 2025). "CFTR channel dysfunction likely results in excessive inflammatory responses to infection often leading to progressive bronchiectasis and decline in lung function in pwCF." (PMID 39903773, 2025). "At present, the guidelines recommend CFTR sequencing (for CF) or gene-panel sequencing (for PCD) for hereditary bronchiectasis." (PMID 40128832, 2025).
bronchiectasis (continued). "Clinical re‐evaluation for other symptoms of CFTR‐related disorders (i.e., bronchiectasis or pancreas insufficiency) or mild CF is indicated in these patients." (PMID 39180390, 2025). "At age 56 years, the participant had obstructive lung disease and bronchiectasis, qualifying for Elexacaftor/Tezacaftor/Ivacaftor (ETI) CFTR modulator treatment due to their F508del allele." (PMID 37325471, 2023). "CFTR and ENaC also play an important role in the pathogenesis of chronic rhinosinusitis and bronchiectasis." (PMID 37175488, 2023). "Among the clinical entities included into the CFTR-RD spectrum, disseminated bronchiectasis is regarded as one of the most worrying complications during childhood." (PMID 35627274, 2022). "The occurrence since early childhood of multiple bronchiectasis, recurrent bronchitis and pneumonia, thick mucus with P. aeruginosa colonization, biliary sludge, and cholelithiasis was suggestive of CFTR-RD." (PMID 35627274, 2022). "In the CF lung, the defective CFTR ion transport results in characteristic static mucus accumulation which eventually progresses to bronchiectasis." (PMID 36359406, 2022). "It is known that patients with residual CFTR channel activity can still develop bronchiectasis with chronic sino-pulmonary infections and other CF-related diseases when they get older." (PMID 33567498, 2021). "Two CF-SPID cases evolved to CF (at two years), while eight evolved to CFTR-related disorders (CFTR-RD), between one and eight years, with bronchiectasis (two), recurrent pneumonia (four, two with sinonasal complications), recurrent pancreatitis (two)." (PMID 32784480, 2020). "While inflammation in CF is believed to be driven predominantly by infection, many CFTR mutant animal models have shown that airway inflammation and bronchiectasis can occur under sterile conditions." (PMID 31532390, 2019). "Physicians taking care of bronchiectasis patients should be aware of CFTR testing and its limitations in the adult population." (PMID 30151190, 2018). "Over the last decades, different investigators evaluated the role of CFTR in adults with bronchiectasis." (PMID 30151190, 2018). "Mutations in the cystic fibrosis transmembrane conductance regulator (CFTR) gene are causative for CF lung disease and drive the earliest pathogenic events in epithelial cells that ultimately lead to the genesis of bronchiectasis." (PMID 29788954, 2018). "An individualized approach is necessary to understand the occurrence and contribution of ion channel functional status in bronchiectasis with the aim to evaluate the overall functionality of CFTR and, possibly, other ion channels." (PMID 30151190, 2018). "Exclusion of CF is imperative for patients with bronchiectasis and CFTR testing should be implemented in usual screening for investigating bronchiectasis etiology." (PMID 30151190, 2018). "The CFTR gene has been previously reported for its involvement in asthma and bronchiectasis, in addition to its possible involvement in severe conditions, such as chronic obstructive pulmonary diseases." (PMID 23554779, 2012). "This intermediate phenotype was characteristic for the whole study population of 100 people with idiopathic bronchiectasis irrespectively of whether clinical features of CFTR dysfunction had been recognized before in an individual." (PMID 41776502, 2026). "The presence of early bronchiectasis on imaging, a clinical feature, but without obvious symptoms, associated with two known pathogenic variants in CFTR and a positive sweat chloride test, were consistent with the diagnosis of early or mild CF." (PMID 40861057, 2025). "In both cases, the team concluded that two flavonoids might have potential use for the treatment of CFTR‐related diseases like CF and bronchiectasis." (PMID 41070403, 2025). "In the same study, the p.Trp493Arg gain-of-function mutation in α-ENaC was found in a female patient with idiopathic bronchiectasis and no mutation in the CFTR gene." (PMID 37175488, 2023).
bronchiectasis (continued). "Is CFTR dysfunction only an ‘instigating factor’ in the pathogenesis of bronchiectasis?" (PMID 37323158, 2023). "This suggests that CFTR modulators may potentially attenuate further progression of bronchiectasis and reverse airway wall thickening and dilation in PwCF." (PMID 37113757, 2023). "The demonstration of improvements in air trapping but worsening of bronchiectasis scores on LUM/IVA are original and underline the importance of collecting real world imaging data and the ongoing development and testing of more effective CFTR modulators." (PMID 37568199, 2023). "In our patient, the presence of biliary sludge and cholelithiasis, and bronchiectasis with repeated P. aeruginosa colonization are also undoubtedly related to the CFTR-RD, which prompted the inclusion of the patient into a dedicated program of surveillance and follow-up." (PMID 35627274, 2022). "Heterozygous carriers of a single CFTR mutation may also be more susceptible to NTM lung infection, particularly with respect to bronchiectasis." (PMID 35889173, 2022). "CFTR-RD is diagnosed when a patient shows disseminated bronchiectasis, recurrent pancreatitis, or congenital bilateral absence of the vas deferens together with only one CF causing CFTR mutation or borderline SCC levels." (PMID 34213646, 2021). "However, a previous study in the United States involving adult patients with bronchiectasis, including MAC-PD, showed a significantly elevated prevalence of CFTR mutations when they were screened for an expanded range of polymorphisms." (PMID 32370226, 2020). "Interestingly, some complications as recurrent pancreatitis, recurrent pneumonia, bronchiectasis, chronic sinusitis and nasal polyps justified diagnosis as CFTR-RD in patients previously recorded as CF-SPID." (PMID 32784480, 2020). "In term of pathophysiology, the CF group is characterized by abnormal CFTR whereas different pathophysiology underlines the non-CF bronchiectasis." (PMID 31194748, 2019). "Further studies on CFTR expression in human lung and translational research might elucidate the possible role of CFTR in the pathogenesis of bronchiectasis." (PMID 30151190, 2018). "Further studies on CFTR expression in human lung and traslational research might elucidate the role of CFTR in bronchiectasis." (PMID 30151190, 2018). "This suggests that it is of importance to identify the most appropriate patient phenotypes involving differentiation based on the level of concomitant emphysema, bronchiectasis and disease severity, the status of smoking, and baseline CFTR function (and/or CFTR genotype)." (PMID 29849907, 2018). "Diffuse bronchiectasis are a possible phenotype of CFTR related disorders." (PMID 24621136, 2014). "Based on their clinical characteristics (only obstructive azoospermia and bronchiectasis), values of CFTR colonic function (within the normal range) and CFTR genotypes, these two individuals were thus classified as CFTR-RD and both 4428insGA and D1152H were regarded as CFTR-RD mutations." (PMID 23082198, 2012). "Also, four carriers had a high suspicion of CFTR-RD, with bronchiectasis or emphysema and intermediate sweat test, although due to the lack of another CFTR mutation and a second functional test, definite diagnosis has not been made." (PMID 40301948, 2025). "Given that there are at least 10 million CF carriers in the United States alone and that a substantial proportion of people with bronchiectasis have CFTR mutations, a better understanding is needed of the role that CFTR function may play in the development of bronchiectasis." (PMID 38390464, 2024). "Moreover, the c.2657+5G>A mutation has been detected in several patients with CFTR-related disorders (such as congenital bilateral absence of vas deferens (CBAVD), bronchiectasis, or pancreatitis) carrying a CF-causing mutation in trans (CFTR-France database)." (PMID 35650428, 2022).
bronchiectasis (continued). "It was also found that CFTR gene mutations altering RNA splicing and/or functional chloride conductance were likely to contribute to the susceptibility and pathogenesis of adult bronchiectasis and pulmonary non-tuberculous mycobacterial infection." (PMID 34086689, 2021). "In detail, within group A, all seven subjects diagnosed as CFTR-RD had an intermediate ST (i.e., between 41 and 53 mmol/L), two CFTR mutations, recurrent or chronic pancreatitis (four cases), bronchiectasis at TC scan (two cases), or congenital bilateral absence of the vas deferens (1 case)." (PMID 33260873, 2020). "CF patients have access to respiratory therapies that patients with bronchiectasis have not formal indication for and those with specific mutations might benefit from new CFTR modulator therapies." (PMID 30151190, 2018). "Mutations in the CFTR gene may also lead to atypical and less severe forms of disease, such as isolated congenital bilateral absence of the vas deferens (CBAVD), chronic pancreatitis or bronchiectasis, regrouped under the term of « CFTR-related disorders » (CFTR-RD)." (PMID 26900683, 2016). "Although we could not identify an association between severe CFTR genotype and progression of bronchiectasis in our cohort aged 9–24 years, we must acknowledge our small sample size, which may have resulted in inadequate power to detect this association." (PMID 27108295, 2016). "Doubts about the original CF diagnosis might also arise from the presence of interstitial infiltration in the lung in the absence of bronchiectasis and of CFTR dysfunction-causing mutations in this patient." (PMID 24621136, 2014). "The mutant CFTR channel does not transport antioxidants to counteract neutrophil-associated oxidative stress, which contributes to the pro- and anti-inflammatory cytokines imbalance responsible for damages in CF lung tissues (bronchiectasis and bronchomalacia) and progressive lung function decline." (PMID 34944110, 2021). "Although bronchiectasis, a classical consequence of dysfunctional CFTR, was listed among the top, it did not meet our significance threshold when corrected for multiple testing." (PMID 38515211, 2024). "Patients with monosymptomatic presentations (pancreatitis, absence of vas deferens, or bronchiectasis), where CFTR dysfunction does not meet CF criteria, are categorized as having CFTR-Related Disorders, conditions resembling CF symptoms." (PMID 38611676, 2024). "Propension to Th17 differentiation for T-cells with consecutive increased Th17 inflammation (able to regulate pIgR mRNA) is a phenomenon present both in CF and non-CF bronchiectasis, possibly not only related to the CFTR defect." (PMID 34944110, 2021). "For instance, in a CFTR knockout ferret model, inflammation, bronchiectasis and mucus accumulation can develop in the absence of infection." (PMID 31532390, 2019). "CFTR-RD is usually related with three major clinical phenotypes: CBAVD (congenital bilateral absence of the vas deferens) with CFTR dysfunction, acute recurrent pancreatitis with CFTR dysfunction and disseminated bronchiectasis with CFTR dysfunction." (PMID 30151190, 2018). "We propose that the ability of P. aeruginosa to chronically infect the lungs of patients with CF, pneumonia, COPD, and bronchiectasis is due in part to the secretion of OMV containing Cif, which inhibits CFTR mediated chloride secretion and thus, reduces the mucociliary clearance of pathogens." (PMID 21455491, 2011). "Effective CFTR modulators will likely slow or at best, halt disease progression, but will not reverse a disease that has already become fixed, examples being pancreatic destruction in the majority, bronchiectasis and absence of the vas deferens." (PMID 36755044, 2023).
bronchiectasis (continued). "According to McCuaig and Martin, deficient ion transport across CFTR in patients with CF cannot be solely responsible for the altered ASM physiology, as there is as much smooth muscle hypertrophy in pediatric CF patients as in those with non-CF bronchiectasis." (PMID 35633979, 2022). "It is not known, however, whether the one defective CFTR gene increases the susceptibility to NTM, bronchiectasis, or both." (PMID 35889173, 2022). "Isolated manifestations, called CFTR-related disorders (CFTR-RD), such as congenital absence of vas deferens, idiopathic chronic pancreatitis, bronchiectasis, among others could be present as well." (PMID 34740355, 2021). "In addition to chronic sinusitis, three phenotypes are included in the CFTR-RD category: CBAVD (congenital bilateral absence of the vas deferens) causing male infertility, acute recurrent or chronic pancreatitis, and bronchiectasis." (PMID 32276344, 2020). "However, no mutations in the cystic fibrosis transmembrane conductance regulator (CFTR) gene were found, while a chest computed tomography scan revealed bronchiectasis and pulmonary nodules." (PMID 30386345, 2018). "Studies of CF families and wide availability of CFTR genetic testing in various populations reveal that CFTR variants are also associated with a wide variety of disorders that do not meet criteria for CF, especially CP (including RAP), bronchiectasis and male infertility." (PMID 36046477, 2022). "Mechanistically, a compelling body of study has suggested that the acquired CFTR dysfunction induced by CS and its increased oxidative stress at least in part plays a pathogenic role in obstructive airway diseases other than the CF, such as COPD, nonatopic asthma, and non-CF bronchiectasis." (PMID 29849907, 2018). "However, given that not all PWCF will benefit from modulator therapies and as inflammation will proceed particularly in established bronchiectasis, most PWCF are likely to benefit from anti-inflammatory therapies irrespective of CFTR modulator treatment." (PMID 32887484, 2020). "Defective CFTR functionality has been associated with failure to eradicate inhaled bacteria; thus, it is conceivable that CFTR impairment by LasB could favor the establishment of chronic P. aeruginosa colonization not only in CF patients but also in patients with COPD and non-CF bronchiectasis." (PMID 33510733, 2020).